CCL2 (C-C motif chemokine ligand 2)
Diseases named in the same sentence as CCL2 in open-access papers (continued):
Sharing a sentence is not in itself a finding about the gene and the disease.
cancer (continued). "We did not observe an increase in CCL2 in HCC patients, but this does not rule out its contributory role during carcinoma development." (PMID 40731922, 2025). "In this study, high levels of plasma VEGF-A, TNF-α, CCL2, IL-6, and IFN-γ in the Cancer TIF1-γ-DM group, particularly those not undergoing any anticancer treatment, were excellent in distinguishing cancer among the anti-TIF1-γ antibody-positive DM patients." (PMID 36357631, 2023). "In the Boyden chamber experiments with or without the monocyte chemoattractant protein-1 (MCP-1/CCL2), THP-1 cells co-cultured with STC1-overexpressing cancer cells showed a significant reduction in migration." (PMID 33156861, 2020). "Positive correlation with cancer-promoting genes BCL2, BCLxL, HIF1A, VEGFA, ACTA2, CCL2, PTGS2, and CDKN1A, but not Ki67, was demonstrated, particularly for ILs’ receptors." (PMID 32512917, 2020). "No major alterations were found between the levels of the pro-inflammatory TNF, IL6, CCL2 and CCL5 and of the anti-inflammatory CD163 in macrophages cultured in the presence of cancer cells, with or without radiation exposure." (PMID 27513864, 2016). "Interestingly, plasma VEGF-A, TNF-α, CCL2, IL-6, and IFN-γ cytokines levels were significantly enhanced in the Untreated Cancer TIF1-γ-DM group than in the Non-cancer TIF1-γ-DM group." (PMID 36357631, 2023). "VEGF-A, TNF-α, CCL2, IL-6, and IFN-γ plasma levels were significantly higher in the Cancer TIF1-γ-DM group, especially those without any anticancer treatment, than those in the non-cancer TIF1-γ-DM and HC groups." (PMID 36357631, 2023). "Finally, by using a cytokine array, we verified that the release of other chemokines and interleukins, such as IL6, IL8, CCL2, CCL5, known to be involved in crosstalk between CAF and cancer cells, was not statistically different between CAF-S1 and CAF-S4." (PMID 31964880, 2020). "For CCL2, there was no significant regulation in both HEK and the investigated cancer cell lines." (PMID 30266096, 2018).
inflammation (166 papers, 2004 to 2025). Aberrant reaction of the microcirculation characterized by movement of fluid and leukocytes from the blood into extravascular tissues. "LncRNA CCL2 is a cis-regulatory lncRNA that regulates the expression of CCL2 gene, which encodes monocyte chemoattractant protein 1 that facilitates monocyte recruitment and promotes the progression of vascular inflammation." (PMID 33922114, 2021). "Furthermore, our studies demonstrate that proteases in poultry dust induce, in addition to IL-8 and IL-6, other genes implicated in lung inflammation such as IL-1β, CCL2, ICAM-1, PTGS2 and TLR4 in alveolar as well as bronchiolar epithelial cells." (PMID 27770804, 2016). "In our experiments, animals in the aerosol group that did not ingest the antigen displayed intense bronchial eosinophilic infiltration and high eosinophilic peroxidases (EPO) and specific IgE activity; elevated IL-4, CCL-11, and CCL-2 are associated with airway inflammation." (PMID 23724232, 2011). "Consistent with liver inflammation, the serum levels of pro-inflammatory proteins, including CCL2, CXCL9, IL-17a, IL-17f, and TNF receptor superfamily member 12a, were increased in HF-HC-fed mice." (PMID 41362710, 2025). "GM-CSF promotes the influx of myeloid cells, CCL2 is known to recruit monocytes, CCL3 has a role in lung inflammation and lymphocyte recruitment, and CCL7 can be linked to acute neutrophilic lung inflammation." (PMID 37600776, 2023). "In vitro, co-culture of differentiated 3T3-L1 adipocytes and RAW264 macrophages is used as the model of adipose inflammation in which pro-inflammatory cytokine genes and proteins such as CCL2, IL-6 and TNF-α are significantly upregulated." (PMID 26901838, 2016). "Our previous study of airway inflammation has demonstrated that the induction of IL-6 and CCL2 upon the interaction of basophils and bronchial epithelial cells under IL-17A stimulation was differentially regulated by ERK, JNK, p38 MAPK, and NF-κB pathways." (PMID 24782592, 2014). "Several reports have demonstrated that CCL-2 plays an important role in the development of pulmonary inflammation and fibrosis in both animal models and human studies." (PMID 25092105, 2014). "Using the LPS-AKI model, we found that administration of nicotinic agonists blunted kidney inflammation (e.g. TNFα, CCL2, and CXCL10)." (PMID 22586448, 2012). "To define possible mechanisms underlying lung damage in DSS-treated TCRδ-/- mice, we analyzed the expression of genes encoding cytokines and chemokines known to contribute to predominately neutrophilic lung inflammation including Csf3, Cxcl2, Il17a, and the monocyte chemoattractant Ccl2." (PMID 37063825, 2023). "Pancreatic inflammation in mice deficient in IFNAR1 ubiquitination was paralleled with an altered balance between pro-inflammatory and anti-inflammatory cytokines (e.g. TNFα and IL10) and increased expression of CCL2." (PMID 24480543, 2014). "In order to investigate whether one of the mechanisms of HIF-1-mediated lung inflammation is via upregulation of the pro-inflammatory chemokine CCL2, we analyzed the effect of EDHB on airway inflammation in combination with OVA." (PMID 22823210, 2012). "Furthermore, folic acid and choline reduced CCL2 mRNA levels, demonstrating that folic acid may help control the progression of chronic inflammation in inflammation-related diseases." (PMID 38629070, 2024). "Similarly, BLM injection significantly increased the serum level of SP-D (lung injury marker secreted by alveolar epithelial type II cells) and the wet weight of the left lung and Ccl-2/Mcp-1 and Il-6 mRNA expression in the lung, indicating the progression of lung inflammation." (PMID 36050717, 2022). "Chronic inflammation is involved with dysregulation of numerous inflammatory cytokines (IL-1β, IL-6, IL-8, TNF-α, NF-κB, IFN-γ, CCL2, MCP1, and CXCL1)." (PMID 37476884, 2023).
inflammation (continued). "The chemokines CCL2 and CCL7 are known as chemotactic agents for monocytes and they have been found to play a key role in mediating lung inflammation." (PMID 33076408, 2020). "Notably, IL-6, CCL2, GM-CSF, and KC/IL-8 have been identified as key biomarkers of ALI and ARDS, owing to their critical roles in the pathogenesis of pulmonary inflammation, endothelial and epithelial injury, and immune cell recruitment." (PMID 41316271, 2025). "LPS-induced acute lung inflammation was significantly exacerbated in Spred-2−/− mice compared with WT mice, as indicated by the numbers of infiltrating leukocytes, levels of alveolar TNF-α, CXCL2 and CCL2 in a later phase, and lung pathology." (PMID 25275324, 2014). "Bindarit is an anti-inflammatory agent that inhibits MCP-1/CCL2, MCP-3/CCL7 and MCP-2/CCL8 synthesis, acting through the down-regulation of NF-kB pathway, that shows potent anti-inflammatory activity in animal models of both acute and chronic inflammation." (PMID 23077623, 2012). "An intentional two-fold expansion of alveolar macrophage numbers by intratracheal CCL2 following intraperitoneal endotoxin did not exacerbate the development of acute lung inflammation in response to intratracheal endotoxin compared to mice challenged only with intratracheal endotoxin." (PMID 16503998, 2006). "Also, IL-31 alone or in combination with IL4 or IL-13 could elevate the expression of epidermal growth factor (EGF), vascular endothelial growth factor (VEGF) and monocyte chemoattractant protein-1 (MCP-1/CCL2) from human bronchial epithelial BEAS-2B cells, which contribute to airway inflammation." (PMID 30647024, 2019). "Previously, we showed that monocytes were exclusively recruited to the brain vasculature in mice with liver inflammation, not neutrophils, and this recruitment led to increased levels of tumor necrosis factor (TNF) and CCL2 within the CNS." (PMID 35379260, 2022).
kidney disease (146 papers, 2006 to 2025). "Recent studies have shown that baseline urine CCL2 levels are good predictors of the risk of progression to a variety of kidney diseases." (PMID 39492831, 2024). "Urine is an easily obtainable sample that can reflect the severity of kidney disease, making it a focus for studying CCL2 levels as a diagnostic tool and for predicting prognosis." (PMID 39850880, 2024). "ALPK1 is known to be associated with kidney disease through association studies, and its expression in animal models can regulate the release of the chemokines CCL2 and CCL5 in kidney cells." (PMID 35505381, 2022). "We find that Twist1 was upregulated in the damaged glomerulus in human kidney disease and murine models and that Twist1 in the murine podocyte limited CCL2-dependent macrophage accumulation, podocyte loss, and albuminuria." (PMID 34369383, 2021). "CCL2 plays a central role in recruiting monocytes and macrophages to sites of inflammation and has been associated with the development of glomerular and tubular injury in kidney diseases." (PMID 39996798, 2025). "We show here that this appears to be similar in a prenatal context during kidney development, thereby generalizing the role of CCL2 in kidney disease and expanding it to kidney development." (PMID 39614902, 2025). "CCL2, also known as monocyte chemoattractant protein-1 (MCP-1), is a pivotal mediator of monocyte and macrophage migration and assumes an essential function in the pathological process of renal diseases related to inflammation and AKI." (PMID 37759588, 2023). "CCL2 plays an important role in many inflammatory diseases and is involved in the development of renal diseases." (PMID 37382267, 2023). "CCL-2 is a well-studied chemokine in cardiac and renal diseases, known for its ability to attract monocytes, T lymphocytes, and natural killer cells." (PMID 37958859, 2023). "CCL2 is the main chemokine driving leukocyte infiltration and monocyte recruitment during acute and chronic inflammatory response in the kidney disease." (PMID 37446007, 2023). "The molecules CXCL-8 and CCL-2 have been described as participating molecules in kidney disorders of different orders, such as lupus nephritis, where the urinary excretion of CXCL8 is related to renal inflammatory activity." (PMID 36117588, 2022). "Nonetheless, a review of CCL2 regulation has shown that CCL2 blockade in several models of renal disease has ameliorated the disease." (PMID 33670423, 2021). "A more extensive prospective study evaluating the use of urinary CCL2 to assess improvements in renal function in obese Asian patients with established renal disease is needed." (PMID 31964990, 2020). "For instance, CCL2/MCP-1 and CXCL8/IL-8 are the chemokines more commonly associated with pediatric renal diseases." (PMID 24692841, 2014). "Hence, CCL2 is one of the potential markers for liquid biopsy to predict kidney diseases progression." (PMID 39492831, 2024). "Furthermore, animal experimental studies have utilized MCP-1/CCL2 as a therapeutic target to improve preclinical kidney disease outcomes." (PMID 39749340, 2024). "Conversely, reducing protein accumulation in renal disease has been shown to decrease CCL2 levels." (PMID 37958859, 2023). "Finally, the Nephroseq V5 tool was applied to identify the expression level of CCL2, FOS, JUN in kidney diseases, as well as the correlation between CCL2, FOS, JUN expression and renal function in the patients with IgAN." (PMID 35464092, 2022). "Furthermore, CCL2+ cells are found in renal tissue, and urinary CCL2 serves as biomarker in ANCA-associated kidney disease." (PMID 34204207, 2021). "The inhibition of CCL2 can ameliorate the disease in different in vitro and in vivo models as well as in clinical trials of renal disease, suggesting that the inhibition of CCL2 may be a promising strategy to treat patients with renal inflammatory disease." (PMID 32365893, 2020). "CCL2/CCR2 signaling is believed to play an important role in kidney diseases." (PMID 31498850, 2019).
kidney disease (continued). "This further suggests a critical role of the inflammatory CCL2 signal in renal disease." (PMID 31223426, 2019). "However, during a late stage of kidney disease, injured proximal tubule cells can enter a profibrotic, pro-inflammatory status via the expression of CCL2 and the activation of the NF-κB, TNF-, and AP-1 signaling pathways, thus likely serving as contributors to CKD progression." (PMID 40723524, 2025). "Therefore, MCP-1/CCL2 has been targeted in preclinical kidney disease." (PMID 34307414, 2021). "Not all studies support a protective role for Ccl2 deficiency in renal disease." (PMID 29872089, 2018). "The relationship between serum chemokine monocyte chemoattractant protein-1 (MCP-1, or CCL2) levels with kidney disease and subclinical cardiovascular disease (CVD) has not been evaluated in the African American (AA) population." (PMID 23151275, 2012).
cardiovascular disease (144 papers, 2009 to 2025). "CCL2 is also expressed in human atherosclerotic plaques and associated with features of plaque vulnerability, and CCL2 polymorphisms and elevated CCL2 plasma levels are associated with an increased risk of cardiovascular disease and mortality." (PMID 38234375, 2024). "Increased CCL2 expression is commonly associated with renal and cardiovascular diseases, including heart failure, coronary atherosclerotic heart disease, hypertension, cardiomyopathy, and fibrosis." (PMID 37958859, 2023). "Likewise, the association of variations in the ligand CCL2 with cardiovascular disease is also controversial." (PMID 35711383, 2022). "Secondly, the study should be developed on the CCL2 and RANTES genetic polymorphisms evaluation in polish cardiovascular diseases population, as genetical variations can influence the chemokines circulating concentration levels." (PMID 31396527, 2019). "Summary of selected studies investigating the role of CCL2 & CCR2 in cardiovascular diseases." (PMID 36110847, 2022). "Indeed, support for the involvement of MCP-1 (CCL2) in the etiology of human cardiovascular disease is strong." (PMID 34671275, 2021). "We conclude that therapy directed towards Ccl2 signaling may provide a novel therapeutic target to prevent progression renal and possibly cardiovascular disease in RVH." (PMID 29872089, 2018). "Among them, CCR2 and its ligands, CCL2 and CCL7 play an important role, so the main objective of this work was to determine whether genetic variants affecting their activity were associated with cardiovascular disease." (PMID 35711383, 2022). "CCL2, also known as MCP-1 (monocyte chemoattractant protein 1) belongs to the CC chemokines especially involved in the pathogenesis of cardiovascular disease, which was well established in animal models." (PMID 31396527, 2019). "Previous studies have reported a reduction of plasma chemokines (i.e CCL2, CCL4, CXCL8) in patients with cardiovascular disease treated with statins." (PMID 19421322, 2009). "Restrictions concerning the therapeutic benefits of CCL2/CCR2 antagonists and antibodies in the management of cardiovascular disorders encompass the assessment of off-target consequences, toxicity, and the possibility of compensatory activity by alternative receptors." (PMID 39125901, 2024). "It is important to note that while the association of CCL2 upregulation in CRS type 4 models has not been addressed to date, its role in cardiovascular diseases suggests that it may represent a potential risk factor for developing CRS type 4." (PMID 37958859, 2023). "In addition, high levels of circulating CCL2 are related to increased long-term cardiovascular mortality in people without significant cardiovascular disease." (PMID 36110847, 2022).
metabolic disorders (72 papers, 2010 to 2026). "CCL2 signaling is associated with metabolic disorders during the development of NASH and contributes to lipid accumulation in hepatocytes." (PMID 39568749, 2024). "In contrast, inhibiting this activation by neutralizing CCL2 can effectively alleviate acute liver injury, which further establishes a clear intrinsic link between ammonia metabolism disorders and immune activation." (PMID 41299729, 2025). "During metabolic disorder, CCL2 and MCP-1 can activate fibroblast-related macrophages such as phagocytes, Kupffer cells, and macrophages induced by monocytes which result in upregulated metabolic inflammation." (PMID 31205932, 2018). "Although our study did not directly investigate LDL-C, the correlative associations observed with CCL2, HDL-C and TG suggest that they may be important players in the development of metabolic disorders." (PMID 29769661, 2018). "This dysfunction promotes metabolic disorders via a mild, chronic inflammation which is characterized by an increased expression of pro-inflammatory factors such as leptin, TNFα, IL6 or monocyte chemoattractant protein-1 (MCP-1 — also known as CCL2)." (PMID 34646852, 2021).
bacterial infection (68 papers, 2005 to 2025). "An alteration in CFTR function results in the activation of the NF-kB pathway and the secretion of several cytokines such as chemokine (C-C motif) ligand 2 (CCL2) upon bacterial infection or lipopolysaccharide stimulation." (PMID 36979360, 2023). "In vivo, CCL2 is one of the main chemokines induced in osteoblasts in response to bacterial infections." (PMID 35832412, 2022). "The heat map showed that the gene expression levels of 62 DEGs were upregulated and that some of these genes, such as IL-6, IL-1β, CCL2, CXCL2, CXCL8, and CSF3, are closely associated with host defense responses to bacterial infection." (PMID 31737164, 2019). "CCL2 and lipocalin-2, a protein that is induced by CCL2 and is involved in host defense against bacterial infection, cooperatively generated immunoregulatory CD11c+ DCs (DCreg) from CD14+ monocytes in vitro." (PMID 31921102, 2019). "These genes mediate the macrophage polarization to M1, a common response of macrophages to bacterial infections, which includes genes encoding TNF, IL-1β, IL-6, and CCL2." (PMID 30064361, 2018). "CCL2 and CCL7 are both implicated in monocyte recruitment during bacterial infection with Listeria monocytogenes." (PMID 29953538, 2018). "It has previously been shown that CCL2 Tg mice are prone to develop fibrotic pulmonary lesions in terms of OP, following bacterial infection." (PMID 27282780, 2016). "CCR2 and CCL2 knockout mice therefore cannot mobilize classical monocytes upon bacterial infection and die because they cannot suppress bacterial growth." (PMID 26029924, 2015). "Whether a bacterial infection superimposed upon a injured brain alters CCL2/CCR2-mediated monocyte activity remains unclear." (PMID 38720343, 2024). "Because the epithelium is the first line of defense against bacterial infection and we found that PFWE inhibited the expression of IL-6 and CCL2/MCP-1 genes in the LPS-challenged lungs in mice, we further investigated the potential mechanisms." (PMID 35815275, 2022). "Second trimester placental explants (16–20 weeks, n = 5/group) were treated with lipopolysaccharide (LPS, to mimic bacterial infection) and ACE2, CCL2, IL-6/8 and TNFα mRNA was assessed." (PMID 34359894, 2021). "Classical type 1 cytokines and chemokines (e.g., IL-2, IL-12, IFN-γ, TNF-α, MCP-1/CCL2, MIP-1α/CCL3, and RANTES/CCL5) were predominantly induced around the peak of bacterial infection, and then decreased as bacterial replication was controlled at 28 dpi." (PMID 27479584, 2016). "In CCR2 knockout mice, and to a lesser extent CCL2 knockout mice, classical monocytes do not enter the bloodstream efficiently and instead accumulate in the bone marrow after bacterial infection." (PMID 26029924, 2015). "However, treatment with resveratrol did not change the levels CCL2 and IL-12p70 or slightly changed the levels of IL-6, upon bacterial infection." (PMID 30971927, 2019). "MCP-1, also known as CCL2, belongs to the CC chemokine family, which could recruit monocytes, memory T cells, and dendritic cells to the sites of inflammation after bacterial infection." (PMID 30029650, 2018).